APOBEC4 (apolipoprotein B mRNA editing enzyme catalytic polypeptide like 4)
Description:
Putative deaminase whose physiological substrate is not yet known.
Synonyms: C1orf169; MGC26594; FLJ25691; RP1-127C7.4
Tractability: No criterion of Open Targets' tractability assessment is met for any kind of drug.
Gene: Protein-coding gene on chromosome 1 (183,646,275 to 183,653,316, reverse strand). Ensembl gene ENSG00000173627.
Pathways (Reactome):
Metabolism of RNA: Formation of the Editosome; mRNA Editing: C to U Conversion
Gene Ontology:
Molecular function: protein binding
Genetic constraint (gnomAD): Loss-of-function variants: 0 observed, 1.85 expected, observed/expected ratio (o/e) 0, 90% interval 0 to 1.41. That is too few expected variants to judge how well the gene tolerates losing a copy. Missense variants: 375 observed, 466.72 expected, observed/expected ratio (o/e) 0.8, 90% interval 0.74 to 0.88. Synonymous variants: 141 observed, 163.59 expected, observed/expected ratio (o/e) 0.86, 90% interval 0.75 to 0.99.
Homologues: Orthologues: chimpanzee APOBEC4 (98% identical), macaque APOBEC4 (92% identical), dog APOBEC4 (82% identical), pig APOBEC4 (80% identical), rat Apobec4 (62% identical), mouse Apobec4 (61% identical), tropical clawed frog apobec4 (45% identical).
Diseases named in the same sentence as APOBEC4 in open-access papers:
APOBEC4 is named in the same sentence as 2 diseases in open-access papers, as found by Europe PMC text mining. Sharing a sentence is not in itself a finding about the gene and the disease. The quoted sentences say what the papers report.
breast carcinoma (1 paper, 2015). "In addition, except the APOBEC3H gene, we found high DNA methylation levels of the remaining APOBEC members, including APOBEC1, APOBEC2, APOBEC3A, APOBEC4, and AICDA, in both HMEC and ER− breast cancer cells." (PMID 26682542, 2015). "For other APOBEC family members, they show either extremely low (median log2-transformed RPKM < 0) mRNA levels (including APOBEC3A, APOBEC3H, APOBEC1, APOBEC2, APOBEC4, and AICDA), or no obvious expression differences between ER+ and ER− breast cancers (including APOBEC3D, APOBEC3F, and APOBEC3G)." (PMID 26682542, 2015).
APOBEC4 also shares sentences with these, for which no sentence is quoted: cancer (1 paper).